NRIP1 (nuclear receptor interacting protein 1)
Diseases named in the same sentence as NRIP1 in open-access papers (continued):
Sharing a sentence is not in itself a finding about the gene and the disease.
cancer (28 papers, 2007 to 2024). A tumor composed of atypical neoplastic, often pleomorphic cells that invade other tissues. "Disruption of NRIP1 function has been reported to lead to hyperactivation of AR signaling, and variants in NRIP1 have been linked to risk in breast, endometrial, and other cancers." (PMID 26485759, 2015). "NRIP1 also participates in the regulation of key steps and various oncogenic signaling pathways during cancer initiation and progression, especially in breast, ovary, liver, and colon tumors, and the development of atherosclerosis." (PMID 37760534, 2023). "The impact of NRIP1 on HCC has been studied, and findings indicate that decreased levels of NRIP1 (both mRNA and protein) can lead to increased growth and migration of cancer cells in HCC." (PMID 37760534, 2023). "Here, we noticed circ_NRIP1 was a recently identified circRNA and acted as a natural ceRNA for miRNAs in cancers." (PMID 33957921, 2021). "Ligand-dependent corepressor (LCoR) and receptor-interacting protein 140 (RIP140/NRIP1) play an important role in the regulation of multiple oncogenic signaling pathways and the development of cancer." (PMID 32157438, 2020). "NRIP1 is a co-regulator for various nuclear receptors and transcription factors shown to be involved in various human cancers." (PMID 26492163, 2015). "In our current report, we also found evidence at the protein level that luminal cancers have higher NRIP1 expression than basal cancers, while the NRIP1 level in HER2 positive cancers is higher than basal cancer but lower than the luminal cancers." (PMID 26492163, 2015). "Analysis of the general immunostaining score indicated that benign and malignant tumors had significantly higher NRIP1 expression levels than CANT (P < 0.001)." (PMID 26492163, 2015). "Analysis of tissue arrays found that NRIP1 is elevated in tumors compared to cancer adjacent normal tissue." (PMID 26492163, 2015). "Despite this increasing evidence for the role of NRIP1 in the progression and development of cancer, the mechanisms are poorly understood." (PMID 26492163, 2015). "NUR77 is frequently elevated in cancers and NRIP1 promotes mitogenic signalling in the developing mammary gland, while SMAD3 and STAT3 are known to be fundamental mediators of growth factor and cytokine signalling." (PMID 25261374, 2014). "These outcomes might support a tissue-specificity of circ_NRIP1 expression, suggesting that the emerging research of circ_NRIP1 in human cancers was still nascent." (PMID 33957921, 2021). "The suppression of NRIP1 in human cancer cells using siRNA may induce apoptosis and inhibit cell growth." (PMID 26492163, 2015). "All the significant nine representative terms covered 16 genes with 6 NCG cancer genes CTNNB1, PML, RB1, MLL2, ARNT and NRIP1 belonging to at least three representative terms." (PMID 34504716, 2021). "Expression of NRIP1 was primarily limited to the periductal stroma in CANT and benign tumors, while malignant tumors had widespread staining in stromal and epithelial cells." (PMID 26492163, 2015). "Several of the other genes are relevant to cancer—in addition to ERBB2, SKAP1 is an adaptor for Src, DEPTOR regulates the mTOR pathway and NRIP1 is an estrogen-receptor coregulator." (PMID 23260012, 2012). "For many years, we have been deciphering the role of the Receptor-Interacting Protein of 140 kDa (RIP140), also known as the Nuclear Receptor-Interacting Protein 1 (NRIP1), which was initially identified in human cancer cells as a corepressor of the estrogen receptor α." (PMID 34206767, 2021). "RARRES1, NRIP1, GJB2 and others showed a negative correlation with MAPK12 and might be cancer suppressor genes in DLBCL." (PMID 38773060, 2024). "Many E2 regulated genes in other normal and cancer cell types were also regulated in MOE cells including Pgr, Greb1, Csf2, and Dhrs9, while other E2 regulated genes in MCF7 cells were not regulated (Nrip1) or even expressed (Tff1) in MOE cells." (PMID 26879975, 2016).
tumor (27 papers, 2007 to 2026). "Our data implicated that miR-195-5p impeded tumor growth in vivo, whereas the upregulation of CircRNA NRIP1 effectively renovated the impacts." (PMID 34689819, 2021). "The tumor risk was also significantly lower in the Nrip1 deficient mice based on the chi-square test, P < 0.001." (PMID 26492163, 2015). "The log-rank test of the tumor incidence fraction curves found the difference between the wildtype and Nrip1 deficient mice was significant (P = 0.03)." (PMID 26492163, 2015). "While limited literature has shown the association between FIP1L1 and metastases, NRIP1 is involved in the epithelial-to-mesenchymal transition, or EMT, which can lead to tumor migration and invasion." (PMID 41614915, 2026). "In this study, we explore the roles of nuclear receptor-interacting protein 1 (NRIP1) in AML, focusing on its associations with tumor progression and immune infiltration." (PMID 41185559, 2025). "Our study identifies NRIP1 as a multifaceted regulator that promotes AML by driving tumor progression, regulating immune cell infiltration, and modulating ferroptosis, highlighting its role as a novel prognostic biomarker." (PMID 41185559, 2025). "The results showed that IL2RA, DNMT3B, ADRM1, and NRIP1 were highly expressed in tumor tissue compared to normal tissue, while ALDH2, NYNRIN, LSP1, and CALCRL were the opposite." (PMID 38322112, 2024). "Protein levels of p38/JAK2/STAT1 were markedly downregulated in miR-195-5p overexpressed PTC cells/tumor xenografts, whereas circRNA NRIP1 overexpression negated these impacts." (PMID 36230649, 2022). "Expression level of circ_NRIP1 was higher in tumor tissues (n = 42) than normal tissues (n = 42) from ESCC patients." (PMID 33957921, 2021). "In conclusion, our findings suggested that CircRNA NRIP1 was up-regulated in PTC tumor tissues and cell lines, and CircRNA NRIP1 silence strained PTC cell proliferation and invasion and accelerated apoptosis." (PMID 34689819, 2021). "Collectively, our western blot results revealed that miR-195-5p upregulation reduced the protein expression levels of p-p38, p-JAK2 and p-STAT1 in PTC cells and tumor xenografts, CircRNA NRIP1 overexpression reversed those effects." (PMID 34689819, 2021). "Suppression of NRIP1 has been reported to inhibit tumor growth, while expression changes in Luminal A tumors may hold clinical relevance." (PMID 41300329, 2025). "In addition, protein levels of “p-p38, p-JAK2, and p-STAT1” were downregulated in miR-195-5p-overexpressed PTC cells and tumor xenografts, whereas CircRNA NRIP1 upregulation reversed these effects." (PMID 36230649, 2022). "These functions were reversed following circRNA NRIP1 upregulation in PTC cells/tumor xenografts." (PMID 36230649, 2022). "Furthermore, tumor growth of KYSE450 cells in xenograft mice was retarded by circ_NRIP1 silence, as well." (PMID 33957921, 2021). "Strong evidence of the suppressed growth of TPC1 xenografts models was found when there was a rise in miR-195-5p, as testified by the lesser tumor volume in mice inoculated with miR-195-5p in comparison to the control, whereas the effects were rescued by CircRNA NRIP1 overexpression." (PMID 34689819, 2021). "Taken together, circ_NRIP1 knockdown functioned a tumor-suppressive role in ESCC cell malignancy." (PMID 33957921, 2021). "The suppressive role of circ_NRIP1 knockdown in cell growth, migration and invasion in vitro was abated by blocking miR-595; meanwhile, miR-595 overexpression elicited similar anti-tumor role in KYSE30 and KYSE450 cells, which was abrogated by restoring SEMA4D." (PMID 33957921, 2021). "Furthermore, the expression level of circ_NRIP1 was knocked down in xenograft tumor tissues, as accompanied with higher miR-595 and lower SEMA4D." (PMID 33957921, 2021). "Besides, the protein levels of p-p38, p-JAK2 and p-STAT1 were remarkably down-regulated in miR-195-5p overexpressed PTC cells and tumor xenografts, whereas CircRNA NRIP1 up-regulation overturned the impacts." (PMID 34689819, 2021).
tumor (continued). "The expression levels of NRIP1 and APC were significantly lower in tumor tissues than normal samples." (PMID 35473611, 2022). "With sh-circ_NRIP1 transfection, cell growth of KYSE450 cells in nude mice was restrained comparing to sh-NC transfection, as described by lowered tumor volume and weight." (PMID 33957921, 2021). "Next, Pearson’s correlation analysis revealed that a remarkable opposite relationship between CircRNA NRIP1 and miR-195-5p appeared in PTC tumor tissues (r2 = 0.3703, P < 0.0001)." (PMID 34689819, 2021). "In conclusion, CircRNA NRIP1 promoted PTC progression by accelerating PTC cells proliferation, invasion and tumor growth, while impeding apoptosis by way of sponging miR-195-5p and regulating the P38 MAPK and JAK/STAT pathways." (PMID 34689819, 2021). "miR-195-5p upregulation repressed proliferation and invasion capabilities, and accelerated apoptosis of PTC cell lines and restraining the growth of tumor xenografts, while the functions were reversed following CircRNA NRIP1 overexpression in PTC cells and tumor xenografts." (PMID 34689819, 2021). "In this study, we searched the expression profile of CircRNA NRIP1 in PTC tumor tissues and corresponding non-tumorous tissues and explored the possible effects and mechanism of CircRNA NRIP1 on PTC cells in vitro and mice xenograft models in vivo." (PMID 34689819, 2021). "Knockdown of circ_NRIP1 could enhance apoptosis rate and E-cadherin expression, but suppress colony formation, cell viability, migration, invasion, and snail expression in KYSE30 and KYSE450 cells, as well as retarded tumor growth in mice." (PMID 33957921, 2021). "Interestingly, the inhibitions of cell migration and tumor metastasis by NOP14 were shown to be NRIP1-dependent, indicating that NRIP1 might be a major effector transducing NOP14 signaling." (PMID 26213846, 2015). "Overexpression of the putative tumor suppressor miR-125b, which is underexpressed in DCIS, repressed the expression of MEMO1, which is required for ErbB2-driven cell motility (also a target of miR-125b), and NRIP1/RIP140, which modulates the transcriptional activity of the estrogen receptor." (PMID 21375733, 2011).
infection (4 papers, 2020 to 2025). The state of being infected such as from the introduction of a foreign agent such as serum, vaccine, antigenic substance or organism. "Compared with infection with PA alone, transfection with pcDNA-NRIP1 further attenuated cell viability and aggravated cell apoptosis and inflammation, and transfection with si-NRIP1 improved cell viability and reduced cell apoptosis and inflammation." (PMID 35460552, 2022). "Similarly, the results of lung wet to dry weight ratio evaluation suggested that PA infection enhanced lung edema, and interference with NRIP1 expression alleviated PA induced lung edema." (PMID 35460552, 2022). "After infection, however, the NRIP1 protein could sense and bind to p50; this interaction retains the p50-NRIP1 pre-complex in the cytoplasm, allowing subsequent recognition by N receptor in the cytoplasm." (PMID 32244634, 2020). "In the absence of infection, NRIP1 protein usually localizes to the chloroplast." (PMID 32244634, 2020).
adenocarcinoma (3 papers, 2015 to 2024). A common cancer characterized by the presence of malignant glandular cells. "This study suggests that low NRIP1 expression in adenocarcinomas is correlated with poor prognosis." (PMID 26492163, 2015).
autosomal dominant disease (1 paper, 2025). Autosomal dominant form of disease. "It has been confirmed that NRIP1 gene loss-of-function is a new single-gene mutation cause of human autosomal dominant disease." (PMID 38849481, 2025).
benign tumors (1 paper, 2015). "Periductal stroma of benign tumors showed significantly increased NRIP1 expression in the cytoplasm compared to CANT (P < 0.05)." (PMID 26492163, 2015). "Interestingly, in benign tumors NRIP1 levels are higher in the cytosol of stromal cells, but NRIP1 levels are higher in the nuclei of epithelial cells in malignancies." (PMID 26492163, 2015). "Nuclear NRIP1 levels in the epithelium of HER2+ tumors were 15 and 30 times higher than benign tumors and CANT, respectively." (PMID 26492163, 2015).
NRIP1 also shares sentences with these, for which no sentence is quoted: Hepatic steatosis (6 papers); Insulin resistance (6); metabolic disease (4); prostate carcinoma (4); embryonal carcinoma (3); adenocarcinoma of the cervix (2); colorectal tumors (2); haematological diseases (2); hepatocellular carcinoma (2); myocardial infarction (2); neurodevelopmental disorder (2); acute promyelocytic leukemia (1); adenovirus infection (1); amyotrophic lateral sclerosis (1); autism (1); autoimmune disease (1); B cell acute lymphocytic leukemia (1); bladder cancer (1); Cerebral ischemia (1); cervical dysplasia (1); cholesterol metabolism disorders (1); Cognitive impairment (1); Cornelia de Lange syndrome 3 (1); dementia (1); developmental delay (1); Duchenne muscular dystrophy (1); gastric adenocarcinoma (1); heart diseases (1); hyperinsulinemic hypoglycemia (1); hypothyroidism (1).
A further 19 diseases each share a sentence with NRIP1 in 1 paper.